POT1 (protection of telomeres 1)
Diseases named in the same sentence as POT1 in open-access papers (continued):
Sharing a sentence is not in itself a finding about the gene and the disease.
cancer (continued). "Our findings demonstrate that the repression of the RPA-ATR DDR is conserved between POT1b and human POT1, suggesting that similar mechanisms may underly the phenotypes observed in human cancers harboring human POT1 mutations." (PMID 37560909, 2023). "POT1 mutations in the DNA-binding domain have been previously implicated as drivers of cancer." (PMID 35420632, 2022). "Indeed, some human pedigrees with POT1 variants contain individuals who develop cancer but lack the POT1 variant." (PMID 35323213, 2022). "Cancer-associated POT1 mutations by their ability to lengthen telomeres might endow cancer cells with proliferative advantages." (PMID 35727838, 2022). "If some human POT1 mutations alter levels of telomeric foci in children or grandchildren, then this might be linked to cancer development or to a phenotype that is distinct from telomere length and might be regulated by telomeric foci." (PMID 35323213, 2022). "POT1 is the most recurrently mutated gene in the shelterin complex in cancer." (PMID 35409143, 2022). "List of POT1 associated with cancer development in the LFL family." (PMID 36387164, 2022). "Germline and sporadic mutation of POT1 are associated with different human cancers." (PMID 35409143, 2022). "Moreover, previous reports on POT1 germline variants in other cancers connect POT1 deregulation with telomere elongation." (PMID 34769003, 2021). "The low frequency of POT1 germline variants within the healthy population (gnomAD database V2.1, n = 118,479) and a constraint score of 0.18 indicating high intolerance of the protein towards loss-of-function variants strongly suggest a functionally relevant role of POT1 in cancer susceptibility." (PMID 34769003, 2021). "Hence, our study expands the spectrum of cancers known or suggested to be associated with inherited mutations in the POT1 gene." (PMID 32492864, 2020). "Identifying the presence of a somatic POT1 variant may yield prognostic information for some cancers." (PMID 32987645, 2020). "Apart from a reported POT1 gene mutation in cancer, its p.S322L mutation causes CP." (PMID 32033110, 2020). "Indeed, most reports concluded that the cancer predisposition associated with these POT1 alleles is due to genomic rearrangements." (PMID 33258446, 2020). "Cancer genome sequencing identified recurrent POT1 mutations in tumors from multiple tissue types." (PMID 33122293, 2020). "Given the involvement of somatic POT1 mutations in a small proportion of such a wide variety of cancer types, it seems possible that further studies of cancer predisposition genes will result in POT1 being included in gene panels for many more types of familial cancer." (PMID 32987645, 2020). "Interestingly, many of the POT1 variants reported in cancer are in the N-terminal OB-fold domains, which constitute the telomeric DNA binding area." (PMID 32987645, 2020). "Germline and somatic POT1 mutations have been identified in a range of cancer types." (PMID 32987645, 2020). "POT1 was the first identified member of the shelterin complex which is mutated in cancer." (PMID 32033110, 2020). "The known functions of POT1 suggest that there may be multiple ways in which POT1 mutations can contribute to the development of cancer." (PMID 32987645, 2020). "POT1 is also somatically mutated in a number of cancer types." (PMID 32987645, 2020). "Moreover, it seems possible that the propensity for mutations at a range of POT1 amino acid residues to result in telomerase-dependent telomere lengthening accounts for this protein being mutated in cancer more often than other shelterin proteins." (PMID 32987645, 2020). "Mutations in the same domain of the POT1 protein can lead to an array of different human cancers." (PMID 32492864, 2020).
cancer (continued). "Recent data on cancer-associated mutations in POT1 have provided a hint that long telomeres may predispose to cancer." (PMID 33258446, 2020). "To better understand the role of the POT1 cancer-associated mutations in telomere maintenance, we examined the phenotype of HEK293T cells infected with WT or mutant POT1 (same as those used for Southern blot analysis) using fluorescence in situ hybridization (FISH)." (PMID 28393830, 2017). "Little is known about the impact of POT1 genetic variation on telomere function and cancer risk." (PMID 26143636, 2015). "Given that most cancer-associated POT1 mutations are likely to result in a loss of function, the inhibition of POT1 might not be a useful therapeutic strategy, but an analysis of the genetic dependencies of POT1 mutant cancer cells may suggest an effective synthetic-lethal approach to treatment." (PMID 32987645, 2020). "To elucidate the molecular mechanism that underlies the POT1 downregulation-induced inhibition of cell proliferation and tumorigenicity, we evaluated the transcription levels of c-Myc, which plays a critical role in the proliferation and tumorigenicity of cancer cells." (PMID 29546066, 2018). "Located on chromosome 7q31.33 with a length of 120kb, POT1 mutations, both germline and somatic, along with dysregulated POT1 expression, have been identified in several cancer types." (PMID 40666093, 2025). "Due to the rarity of POT1 GPVs and limited available data, the overall lifetime cancer risks for individuals with POT1-TPDS are unclear." (PMID 40350252, 2025). "During the meeting, it was recognised that due to the rarity of POT1-TPDS and LP/P POT1 variants, there is currently a limited evidence base to support surveillance recommendations in terms of early detection and cancer mortality." (PMID 40350252, 2025). "These genetic alterations disrupt the normal function of POT1, a critical component of the shelterin complex, thereby contributing to genomic instability and the progression of cancer through aberrant telomere dynamics." (PMID 39871386, 2025). "Overall, a germline pathogenic variant (gPV) in a cancer predisposing gene was identified in 9.7% of individuals (CHEK2, FANCM, NF1, POT1 and PTEN) and a candidate variant in 4.2% of individuals (HOXB13, MAX and RECQL4)." (PMID 39979679, 2025). "Given the small number of individuals identified with POT1 GPVs, the overall lifetime cancer risks for individuals with a GPV in POT1 are unclear and data on long-term follow-up of identified families are limited." (PMID 40350252, 2025). "In this work, we aim to describe a broader cancer phenotype related to POT1-TPD, in three families (two with a four generation pedigree, one with a five generation pedigree)." (PMID 38839987, 2024). "This case represents an example suggesting the clinical relevance of POT1 alterations and their involvement in a broad range of cancer types and indicates the possibility that management approaches should be evaluated for mutation carriers." (PMID 39156708, 2024). "Lately, increasing evidence shows that long telomeres caused by variants in shelterin components (POT1, TPP1, and RAP1) also display an increased risk of cancer." (PMID 38540414, 2024). "Data regarding involvement of POT1 and DCLRE1B genes in telomeropathies are only recently emerging with proposals that these genes should be included on cancer‐risk predisposing multigene panel tests as well as genetic tests for telomere biology dysfunction." (PMID 37994393, 2024). "When POT1 is mutated, TERRA levels rise, resulting in telomere disruption, linked to various cancer types." (PMID 39578854, 2024). "Our findings broaden the spectrum of POT1‐related cancers and demonstrate the importance of the germline genetic analysis in hematological malignancies." (PMID 36467798, 2022). "Our results support the routine testing of POT1 and other LFL/LFS-associated genes in the risk populations to enable early cancer diagnosis, prevention and intervention." (PMID 36387164, 2022).
cancer (continued). "TRF1 and POT1 amplification and TRF2-RAP1-TPP1 co-amplification/deletion were found to be associated with cancer progression, defining broad molecular signatures linked to several intracellular pathways involved in oncogenesis." (PMID 35409143, 2022). "The extensive personal and family history of cancer in this individual with six tumors, including SMZL, supports a likely oncogenic role for this POT1 variant." (PMID 35456397, 2022). "For example, the protection of telomere 1 (POT1) protein is an important subunit of the Shelterin telomere-binding complex, which can promote the development of various cancers by leading to immortalization." (PMID 35903361, 2022). "Many POT1 mutations implicated in cancer affect the first and second OB folds of POT1, which are homologous to C. elegans POT-1 and POT-2 proteins." (PMID 35323213, 2022). "Nonetheless, as with the other shelterin proteins, upregulation of POT1 has also been detected in cancer." (PMID 33599797, 2021). "As such, POT1 has been identified as a high penetrant gene in these cancers and has been suggested to be included in gene panel testing for families that come in for screening." (PMID 33599797, 2021). "EXTEND scores were positively correlated with POT1 expression across pan-cancer (Rho = 0.22, P < 2.2e − 16)." (PMID 33420056, 2021). "We therefore summarize what is known about the normal function of the POT1 protein, and the nature of the POT1 alterations in human cancer, and consider the insights this provides into cancer biology and potential clinical implications." (PMID 32987645, 2020). "Inherited POT1 mutations in cancer-prone families are associated with excessively long telomeres in somatic cells." (PMID 33258446, 2020). "In our study, either POT1 knockdown or miR-185 overexpression in established cancer cells significantly decreased cell proliferation." (PMID 32687062, 2020). "Some studies suggest that POT1 expression is upregulated in cancer samples compared to healthy controls." (PMID 32987645, 2020). "Here, we review the biological functions of POT1, the prevalence of POT1 germline and somatic mutations across cancer predisposition syndromes and tumor types, and the dysregulation of POT1 expression in cancers." (PMID 32987645, 2020). "Given the limited literature, it is difficult to draw consistent conclusions regarding POT1 expression in cancer." (PMID 32987645, 2020). "In this review, we focus on the role of one of the telomere-associated proteins, Protection of Telomeres 1 (POT1), in telomere function and cancer." (PMID 32987645, 2020). "Some studies suggest that POT1 is overexpressed in radioresistant cell lines of diverse cancer types." (PMID 32987645, 2020). "It is possible that POT1 expression is highly variable across cancer types, and also in some cases within cancer types." (PMID 32987645, 2020). "On one hand, the altered POT1 alleles result in very long germline telomeres in the probands, consistent with the idea that telomere shortening curbs tumorigenesis." (PMID 33258446, 2020). "Recently, several reports have shown that depletion of protection of telomeres 1 (POT1) fuels tumorigenesis and leads to cancer development." (PMID 29546066, 2018). "Our results reveal that in addition to the N-terminal OB folds, the C terminus of POT1 is also required to maintain genome stability to prevent cancer initiation." (PMID 28393832, 2017). "Somatic mutations of POT1 have been reported in CLL, and this represents the first description of a shelterin complex-gene mutation in human cancer." (PMID 27486974, 2016). "Furthermore, the development of a patient information leaflet for individuals carrying POT1 PVs and their relatives is considered of essence, in order to raise patients’ awareness and explain their lifetime cancer risks compared with the general population." (PMID 40851494, 2025). "The inclusion of POT1 in germline panels for various types of cancer is warranted." (PMID 38540414, 2024).
cancer (continued). "POT1 variants reported here, appear to functionally mimic the ssDNA telomere binding defects, similar to POT1 variants described in familial cancer patients without DC or DCL features." (PMID 39198715, 2024). "Mutations in proteins such as POT1 or TRF2 can cause excessive telomerase activity or telomere shortening, resulting in uncontrolled cell proliferation and chromosomal rearrangements that promote cancer." (PMID 39578854, 2024). "Other cancer associated POT1 mutations when introduced in stem cells do not cause significant telomere damage but led to telomere elongation." (PMID 35727838, 2022). "This makes it an attractive target for therapeutic intervention against POT1-related cancers." (PMID 35409143, 2022). "We and others have shown that POT1 mutations found in CLL, melanoma, Hodgkin lymphoma, T-cell lymphoma and LFL syndrome result in longer telomeres and are associated with higher chromosomal instability, another hallmark of cancer." (PMID 35727838, 2022). "The shelterin protein POT1 has been found mutated in many different familial and sporadic cancers, however, no mouse models to understand the pathobiology of these mutations have been developed so far." (PMID 35727838, 2022). "It has been suggested that the upregulation of POT1 was necessary in restoring and maintaining 3′-overhang lengths in telomerase reactivated cancers, so as to prevent DNA damage response activation and to prolong survival and proliferation of cancer cells." (PMID 33599797, 2021). "This is in line with published data from human embryonic stem cells (hESC), in which cancer-associated POT1 mutations did not trigger DNA damage responses but led to longer telomeres." (PMID 34769003, 2021). "Here, we focus on Protection of Telomeres 1 (POT1), the shelterin protein that appears to be most commonly involved in cancer, and consider the clinical significance of findings about its biological functions and the prevalence of inherited and acquired mutations in the POT1 gene." (PMID 32987645, 2020). "However, POT1 mRNA measured by qRT-PCR tended to be downregulated in stage I/II tumors while remaining upregulated in stage III/IV cancers." (PMID 32987645, 2020). "As an example, malfunction of POT1 and DNA damage signaling in cardiac angiosarcoma has been suggested to assist in the acquisition of somatic mutations in the Vascular Endothelial Growth Factor (VEGF) pathway, thus facilitating cancer development." (PMID 32987645, 2020). "Moreover, p.R117C in the POT1 gene is associated with cardiac angiosarcoma (CAS), a rare malignant tumor, whose genetic basis is not fully understood." (PMID 32033110, 2020). "In multiple cancers, POT1 expression has paradoxically been positively correlated with telomere length and telomerase activity, indicating a connection between POT1 dysregulation and cancer telomere pathology." (PMID 32987645, 2020). "Finally, we summarize the clinical implications of POT1 alterations in the germline and in cancer, and possible approaches for the development of targeted cancer therapies." (PMID 32987645, 2020). "Since the POT1 plays a key role in the protection of telomere concerning telomere elongation and cell immortality, it has been considered as a promising drug target for cancer therapy." (PMID 32033110, 2020). "Alterations of POT1 have been detected in a range of cancers." (PMID 32987645, 2020). "While previous work demonstrated the biological mechanism of POT1 in aging and cancer, how POT1 is posttranscriptionally regulated remains largely unknown." (PMID 32687062, 2020). "Cancer-predisposing mutations in the POT1 subunit of shelterin also did not inform on the telomere tumor suppressor pathway because they have two outcomes of potential relevance to cancer." (PMID 33258446, 2020). "Interestingly, several studies have recently shown that POT1 depletion fuels tumorigenesis and leads to cancer development, increases cancer cell proliferation, and enhances tumorigenicity." (PMID 29546066, 2018).
cancer (continued). "Downregulation of POT1 by using siRNA increase human cancer cell radiosensitivity." (PMID 30405890, 2018). "In addition, we identify several missense mutations in human cancers that disrupt the POT1C–TPP1 interaction, resulting in POT1 instability." (PMID 28393832, 2017). "Notably, five ISs were detected within the introns of POT1, a major cancer gene." (PMID 41596377, 2026). "Given the inclusion of POT1 in the National Test Directory in England and the need for UK-based guidance, an expert group undertook a literature review to assess the phenotypic spectrum of POT1-TPDS and to provide lifetime risk estimates of POT1-associated cancers." (PMID 40350252, 2025). "Identifying GPVs in POT1 may help explain a personal or family history of cancer, help tailor early cancer detection and prevention strategies in individuals with a POT1 GPV and facilitate predictive (also known as pre-symptomatic or familial) testing and onward management of at-risk relatives." (PMID 40350252, 2025). "Without robust information on cancer risk and/or the utility of surveillance for POT1 heterozygotes, a more cautious approach to surveillance may be required." (PMID 40350252, 2025). "In addition, the inclusion of POT1 in germline panels for various types of cancer is warranted." (PMID 38540414, 2024). "Therefore, it is not surprising that POT1 malfunction has been linked to the development of various types of human cancer." (PMID 34769003, 2021). "Unfortunately, the therapeutic role of POT1 inhibition in cancer is currently unknown." (PMID 34638300, 2021). "Interestingly, recurrent somatic mutations in the OB-fold domains of POT1 reported causing telomere dysfunction in CLL signifying that alteration of TPP1-telomere binding could lead to genomic instability and cancer." (PMID 32033110, 2020). "Therefore, the POT1 mutations have not provided unambiguous evidence for the idea that long telomeres predispose to cancer." (PMID 33258446, 2020). "However, current evidence for POT1-TPDS is not supportive of an equivalent lifetime cancer risk." (PMID 40350252, 2025). "The protection of telomeres 1 (POT1) protein is an essential subunit of the shelterin telomere binding complex and appears to be most commonly involved in cancer." (PMID 37917279, 2024). "The shelterin complex consists of six proteins, termed TRF1, TRF2, RAP1, TPP1, POT1, and TIN2, and abnormal expression of shelterin has been observed in various types of cancers." (PMID 35757510, 2022). "However, the therapeutic value of POT1 inhibition in cancer is currently unknown." (PMID 32987645, 2020). "A recent pan-cancer study of POT1 mutations categorized genetic variants according to the standards of the American College of Medical Genetics and Genomics, and referred collectively to all POT1 variants that are neither “presumed benign” nor “benign” as “non-benign”." (PMID 32987645, 2020). "It was noted that there is a significant lack of evidence both for the cancer types and cancer risks for individuals with POT1-TPDS." (PMID 40350252, 2025). "POT1, TRF1, and TRF2 were generally upregulated in most cancers." (PMID 39578854, 2024). "Telomeric ends are protected by shelterin complexes, which are composed of six proteins, including TRF1, TRF2, RAP1, POT1, TIN2, and TPP1, and their lengths are maintained by telomerase activity regulated by the complexes, depending on cell type (cancer cells and normal cells)." (PMID 35805162, 2022). "Since his mother’s death at the age of 43 was not cancer-related, it is not clear whether POT1 p.Q199* arose de novo or was maternally transmitted." (PMID 34769003, 2021). "POT1 expression in cancer has not been as well studied as POT1 gene alterations." (PMID 32987645, 2020).